CST9L (cystatin 9 like)
Synonyms: CTES7B; bA218C14.1
Tractability: Antibody: UniProt places it where antibodies can reach, with high confidence; UniProt predicts a signal peptide or a membrane-spanning region; its Gene Ontology location is reachable by antibodies, with medium confidence.
Gene: Protein-coding gene on chromosome 20 (23,564,732 to 23,568,484, reverse strand). Ensembl gene ENSG00000101435.
Subcellular location: Secreted
Gene Ontology:
Molecular function: protein binding; cysteine-type endopeptidase inhibitor activity
Biological process: antimicrobial humoral response
Cellular component: extracellular region
Genetic constraint (gnomAD): Loss-of-function variants: 12 observed, 9.84 expected, observed/expected ratio (o/e) 1.22, 90% interval 0.77 to 1.83. That is too few expected variants to judge how well the gene tolerates losing a copy. Missense variants: 121 observed, 126.52 expected, observed/expected ratio (o/e) 0.96, 90% interval 0.82 to 1.11. Synonymous variants: 62 observed, 53.98 expected, observed/expected ratio (o/e) 1.15, 90% interval 0.94 to 1.42.
Homologues: Orthologues: chimpanzee CST9L (96% identical), macaque CST9L (88% identical), rat Cst9l (46% identical), mouse Cst9 (44% identical), rat Cstdc2 (39% identical), mouse Cstdc2 (37% identical), zebrafish si:busm1-57f23.1 (19% identical), Caenorhabditis elegans cpi-2 (16% identical), Caenorhabditis elegans cpi-1 (12% identical), Caenorhabditis elegans K08B4.7 (5% identical). Paralogues in human: CST9 (44% identical), CST1 (24% identical), CST2 (24% identical), CST3 (24% identical), CST4 (24% identical), CST11 (22% identical), CST5 (22% identical), CSTL1 (21% identical), CST8 (20% identical), CST6 (19% identical), CST7 (19% identical).